MIF (macrophage migration inhibitory factor)
Diseases named in the same sentence as MIF in open-access papers (continued):
Sharing a sentence is not in itself a finding about the gene and the disease.
Down syndrome (2 papers, 2014 to 2019). "In our study, we also showed that in the amniotic fluid of women with fetal Down syndrome when compared to patients with healthy fetus there exists significant decrease in concentration of 3 chemokines, that is, ITAC, MCP-3, and MIF." (PMID 25477715, 2014). "Furthermore, we showed decrease in concentration of 3 chemokines, ITAC, MCP-3, MIF, and increase in concentration of 4 chemokines, IP-10, MPIF-1, CXCL7, and 6Ckine, in amniotic fluid of women with fetal Down syndrome." (PMID 25477715, 2014).
ductal adenocarcinoma (2 papers, 2020 to 2025). "In a mouse model of ductal adenocarcinoma (PDAC), PDAC releases exosomes highly expressing macrophage migration inhibitory factor (MIF), which are engulfed by Kupfer cells and transported from the bloodstream to the liver." (PMID 40534881, 2025).
dyslipidaemia (2 papers, 2024 to 2025). "For example, the association of the inflammatory biomarkers MIF and WBCs with AA‐induced dyslipidaemia, as well as the metabolic proteins asprosin, IGFBP‐2, and APOA1 highlight potential areas for further research." (PMID 41017289, 2025). "The lower MIF levels identified in this study support the existing research and provide a possible pathway via which AA‐induced dyslipidaemia occurs." (PMID 41017289, 2025).
dysplasia (2 papers, 2019 to 2023). A usually neoplastic transformation of the cell, associated with altered architectural tissue patterns. "Only within H. pylori-positive group, MIF level was significantly elevated in patients with cancer than in control or dysplasia groups (P<0.05)." (PMID 30742638, 2019). "MIF level was significantly elevated in cancer subgroup than in control or dysplasia subgroups of patients, only within H. pylori-positive group." (PMID 30742638, 2019). "Tissue MIF level varied remarkably between H. pylori-positive and -negative groups: the MIF level in the H. pylori-positive group was significantly elevated in the cancer subgroup than in control (P = 0.012) or dysplasia (P < 0.01) subgroups." (PMID 30742638, 2019). "Based on in vitro studies reported previously, H. pylori stimulated MIF secretion through its cag PAI, especially in the tumor microenvironment from dysplasia to cancer." (PMID 30742638, 2019). "No statistically significant longitudinal difference in MIF levels was seen between control, dysplasia and cancer subgroups within both H. pylori -positive and -negative groups (P > 0.05)." (PMID 30742638, 2019).
Ewing sarcoma (2 papers, 2025). A small round cell tumor that lacks morphologic, immunohistochemical, and electron microscopic evidence of neuroectodermal differentiation. "Similarly, MIF levels were elevated in adult patients with Ewing sarcoma compared with pediatric patients (2.83 pg/mL vs. 2.50 pg/mL; p < 0.05)." (PMID 41008853, 2025). "MIF and the receptor CD74 can be used as a promising target to treat Ewing sarcoma, which is infiltrated by immunosuppressive myeloid populations." (PMID 40427533, 2025).
falciparum malaria (2 papers, 2006 to 2023). "Among the eight cytokines tested in this large cohort of adults with imported falciparum malaria, only MIF and IL-10 were higher in patients with greater disease severity." (PMID 37365194, 2023).
fibrosarcoma (2 papers, 2007 to 2024). A malignant mesenchymal fibroblastic neoplasm affecting the soft tissue and bone.
Flavivirus Infections (2 papers, 2017 to 2025). Infections with viruses of the genus FLAVIVIRUS, family FLAVIVIRIDAE. "MIF is considered pathogenic in flavivirus infections as MIF-deficient mice were protected in WNV infection and showed lower viral loads and inflammatory responses." (PMID 40918112, 2025).
Fungal infection (2 papers, 2019 to 2023). "Overall, while MIF has been shown to play a complex role in fungal infections, the exact mechanism of action at work and the extent of the MIF contribution to the infection remain under investigation." (PMID 38275363, 2023). "MIF has also been shown to be involved in fungal infections." (PMID 38275363, 2023).
gallbladder cancer (2 papers, 2015 to 2017). "The inhibition of MIF in gallbladder cancer cell line by ISO-1 and 4-IPP or its specific siRNA led to a decrease in the colony forming ability." (PMID 27788497, 2017). "Silencing/inhibition of MIF using siRNA and/or MIF antagonists resulted in a significant decrease in cell viability, colony forming ability and invasive property of the gallbladder cancer cells." (PMID 26530123, 2015). "Our findings support the role of MIF in tumor aggressiveness and suggest its potential application as a therapeutic target for gallbladder cancer." (PMID 26530123, 2015). "In vitro cellular assays were carried out in a panel of gallbladder cancer cell lines using MIF inhibitors, ISO-1 and 4-IPP or its specific siRNA." (PMID 26530123, 2015).
glomerular disease (2 papers, 2018 to 2026). "MIF promoted podocyte injury and MIF targeting was protective in experimental glomerular disease." (PMID 29924850, 2018). "In conclusion, our study addressed the role of MIF and ANGPTL-4 in the pathogenesis and management of nephrotic syndrome, as well as their position as determinants of steroid responsiveness of glomerular diseases." (PMID 40968277, 2026).
gout (2 papers, 2018 to 2023). A condition characterized by painful swelling of the joints, which is caused by deposition of urate crystals. "Moreover, in a mouse model of gout, MIF levels are raised, and MIF deficiency or blockade lowers levels of IL-1β and reduces neutrophil infiltration and pathology." (PMID 30619278, 2018). "There were only 16 pathways active in gout remission, including inflammatory and coagulation-related pathways LIGHT, TWEAK, NOTCH, COLLAGEN, THBS, MIF, and TGF-β." (PMID 38063198, 2023).
Granuloma (2 papers, 2019 to 2025). A compact, organized collection of mature mononuclear phagocytes, which may be but is not necessarily accompanied by accessory features such as necrosis. "Although immunity generally correlates with the formation of intestinal granulomas, we found that MIF−/− mice developed normal numbers of granulomas despite being completely susceptible to infection." (PMID 31708913, 2019). "Conversely, endothelial cells from MAH granulomas were predicted to send MIF signals which promote macrophage survival." (PMID 41586350, 2025). "Finally, Mtb granulomas have more FN1 senescent signaling from endothelial cells but lack MIF and SPP1 signaling for survival compared to MAH granulomas." (PMID 41586350, 2025).
hematoma (2 papers, 2021 to 2025). A hematoma is a collection of blood from a vascular structure into an extravascular space. "Syk potentially mediates Th2-polarized cytokine secretion (Il-6/Il-10), Cd36 enhances hematoma resolution via Il-10/Stat3 signalling and Cd74 synergizes with MIF to amplify inflammatory cascades." (PMID 40623122, 2025). "The correlation between preoperative serum MIF levels and surgical complications, including RLN injury, hypoparathyroidism, and hematoma, was analyzed using the Mann-Whitney U test." (PMID 34575145, 2021).
hepatopathies (2 papers, 2013 to 2021). "In patients with established AOSD, a higher frequency of -794 CATT7 containing MIF genotypes was observed in those with liver dysfunction (P = 0.009)." (PMID 23721694, 2013). "Furthermore, within the current study, expression of MIF mRNA was not increased in patients with AH in GSE28619 or in the second cohort of patients with alcohol-associated steatohepatitis (ASH) and other hepatopathies (data not shown)." (PMID 33945507, 2021).
HIV-1 infection (2 papers, 2018 to 2022). The type species of lentivirus and the etiologic agent of acquired immunodeficiency syndrome (AIDS). "MIF may contribute to viral pathogenesis by generating a microenvironment enriched in activating mediators and Th17-like CD4TLs, which are known to be highly susceptible to HIV-1 infection and relevant to viral persistence." (PMID 36298774, 2022). "Treatment of unactivated CD4+ T-cells with MIF-treated HIV-infected MDM-derived culture supernatants led to enhanced permissiveness to HIV-1 infection." (PMID 29997630, 2018). "However, research on its contribution to HIV immune dysfunction has been limited even in face of the evidence of CD74 and MIF overexpression during HIV-1 infection." (PMID 36298774, 2022).
Hyperinsulinemia (2 papers, 2014 to 2024). An increased concentration of insulin in the blood. "Our current study suggests a positive association between elevated plasma MIF levels and hyperinsulinemia following AAP treatment." (PMID 38802393, 2024). "Increased levels of MIF can enhance insulin secretion in a glucose dependent manner and this may in turn explain the reduced hyperinsulinemia observed in obese MIF−/− mice." (PMID 25412423, 2014).
Hyperoxaluria (2 papers, 2023 to 2024). Increased excretion of oxalates in the urine. "Together, these results suggest that acetate treatment ameliorates the hyperoxaluria-induced renal injury via inhibiting macrophages infiltration with change of the miR-493-3p/MIF signals." (PMID 36922584, 2023). "Importantly, the MIF expression in the kidney was decreased after treatment of acetate in hyperoxaluria rats." (PMID 36922584, 2023).
hyperthyroidism (2 papers, 2020 to 2024). Overactivity of the thyroid gland resulting in overproduction of thyroid hormone and increased metabolic rate. "The presence of interleukin-13 (IL-13) and macrophage migration inhibitory factor (MIF) are causally associated with hyperthyroidism (OR = 1.046, 95% CI: 1.008–1.086, p = 0.019; OR = 1.052, 95% CI: 1.007–1.099, p = 0.022, respectively)." (PMID 38872961, 2024).
hypertriglyceridemia (2 papers, 2024). A laboratory test result indicating elevated triglyceride concentration in the blood. "PAR2-KO mice with reduced plasma MIF levels are protected from hypertriglyceridemia, an effect associated with adipocyte hypertrophy, indicating increased fatty acid uptake and storage." (PMID 38973609, 2024). "Restoration of high plasma MIF levels reverses high LPL in WAT of PAR2-deficient mice, resulting in hypertriglyceridemia." (PMID 38973609, 2024). "MIF-mediated downregulation of adipose lipoprotein lipase contributes to hypertriglyceridemia." (PMID 38973609, 2024). "Further investigation is needed to determine whether LPL is involved in MIF-regulated AAP-induced hypertriglyceridemia in patients with SZ." (PMID 38802393, 2024). "Herein, in the present study, we investigated a hypothesis that PAR2 regulates hypertriglyceridemia through MIF." (PMID 38973609, 2024). "Thus, following high-fat diet feeding, PAR2 deficiency attenuated the rise in plasma MIF levels, reversed LPL expression and activity in WAT, and thus corrected hypertriglyceridemia." (PMID 38973609, 2024). "Furthermore, increased circulating MIF levels play a role in inducing hypertriglyceridemia by downregulating lipoprotein lipase (LPL) in adipose tissue." (PMID 38802393, 2024). "Circulating MIF levels are associated with metabolic dysfunction in the presence or absence of inflammation, but its role in regulating hypertriglyceridemia is currently unknown." (PMID 38973609, 2024). "Recombinant MIF infusion restored high plasma MIF levels in Par2–/– mice, and the levels decreased LPL and attenuated adipocyte lipid storage, leading to hypertriglyceridemia." (PMID 38973609, 2024). "MIF overexpression induces high-circulating MIF levels, thereby suppressing adipose LPL and inducing hypertriglyceridemia." (PMID 38973609, 2024). "Recent findings also indicated that MIF directly inhibits the expression and activity of lipoprotein lipase (LPL) in mouse adipose tissue, thereby impairing LPL’s ability to break down plasma TG, resulting in hypertriglyceridemia." (PMID 38802393, 2024). "However, whether MIF regulates LPL and hypertriglyceridemia was previously unknown." (PMID 38973609, 2024).
inflammatory diseases of skin (2 papers, 2018 to 2021). "This association indicates that the MIF gene could be a common genetic marker of the autoimmune and inflammatory diseases of the skin." (PMID 34533238, 2021). "Further studies in indeterminate leprosy and paucibacillary leprosy, as well as other infectious and inflammatory diseases of skin, are required to describe the participation of MIF/CD74 in the immune response against leprosy in the skin." (PMID 29487601, 2018).
intervertebral disc degeneration (2 papers, 2020 to 2025). "More importantly, MIF could become a new target to prevent and treat intervertebral disc degeneration, which will receive extensive attention and research in the future." (PMID 32517767, 2020). "In the context of intervertebral disc degeneration (IDD), neutrophil infiltration into the extracellular matrix contributes to disease progression through the MIF/ACKR3 axis." (PMID 40756519, 2025).
intestinal inflammation (2 papers, 2011 to 2020). "Next, we found that MIF levels were increased significantly in the intestinal lumen and tissue of mice during DSS-induced intestinal inflammation in mice." (PMID 32004754, 2020).
Kawasaki disease (2 papers, 2014 to 2022). A rare inflammatory disease characterized by an acute febrile, systemic, self-limiting, medium-vessel vasculitis primarily affecting children. "There is also another single nucleotide polymorphism in the promoter of the MIF gene at the position −173 that has been previously analyzed and related to the inflammatory response in coronary bypass surgery and coronary alterations in children with Kawasaki disease." (PMID 25105152, 2014). "On the other hand, the MIF signal, which decreased in our data, also decreased in patients with Kawasaki disease and CoV2-MyoC." (PMID 36225942, 2022).
keloid (2 papers, 2022 to 2025). An irregularly shaped, elevated mark on the skin caused by deposits of excessive amounts of collagen during wound healing. "Overall, the significant signal patterns related to keloid included, but were not limited to MK, MIF, and VEGF." (PMID 36388926, 2022). "In keloid samples, the LAMININ, MIF, SEMA6, and WNT cell interaction signaling pathways were specifically identified as being secreted by P311_fibroblast." (PMID 41350567, 2025).
kidney cancer (2 papers, 2023 to 2024). Primary or metastatic malignant neoplasm involving the kidney. "Macrophage migration inhibitory factor (MIF1 alpha) expression was also measured as a marker for kidney cancer." (PMID 36975533, 2023). "Studies of the role of MIF (which largely functions via the type II transmembrane receptor CD74) in prostate, bladder and kidney cancers suggested that it is a pro-tumorigenic factor in genitourinary malignancy." (PMID 39281682, 2024).
leptospirosis (2 papers, 2021 to 2023). A contagious bacterial infection caused by spirochetes of the genus Leptospira. "Receiver operating characteristic (ROC) analysis of macrophage migration inhibitory factor (MIF) as an early diagnostic marker for leptospirosis." (PMID 35237527, 2021). "A significantly different cutoff point of the serum MIF level (p < 0.001) was detected in leptospirosis patients when compared with other cases, which greatly suggested that MIF is a potential early diagnostic marker for leptospirosis." (PMID 35237527, 2021). "In this case–control study, we determined the disease prevalence and proposed the use of serum MIF as a potential early diagnostic tool to successfully combat the outbreak of leptospirosis in developing countries." (PMID 35237527, 2021). "The aim of the present study was to evaluate the diagnostic value of macrophage migration inhibitory factor (MIF) for leptospirosis." (PMID 35237527, 2021). "It was found that evaluation of the serum MIF levels of patients has diagnostic implications for leptospirosis." (PMID 35237527, 2021). "Taken together, MIF is an early-phase cytokine that could serve as a rapid diagnostic marker for leptospirosis." (PMID 35237527, 2021). "Here, we analyzed whether there was any association between serum MIF and leptospirosis disease progression." (PMID 35237527, 2021). "However, the currently evaluated diagnostic marker (MIF) is an early expressed inflammatory cytokine, which may serve as a promising early diagnostic marker for leptospirosis." (PMID 35237527, 2021). "Our results revealed that the serum MIF levels were more significantly elevated in patients with severe than in those with mild leptospirosis." (PMID 35237527, 2021). "MIF profiling in leptospirosis patients also suggested that an elevated concentration of serum MIF is a superior indicator for predicting severe leptospirosis." (PMID 35237527, 2021). "ROC analysis revealed that the serum MIF levels discriminated significantly between leptospirosis cases and healthy control subjects." (PMID 35237527, 2021). "THP-1 cells and mice with experimentally induced leptospirosis showed significantly upregulated MIF expression at the early phase of leptospirosis." (PMID 35237527, 2021). "The sensitivity and the specificity of serum MIF profiling for leptospirosis cases were found to be 100% and >90%, respectively, in different clinical forms of leptospirosis." (PMID 35237527, 2021). "Our results demonstrated that the levels of serum MIF were significantly upregulated in leptospirosis patients compared to those in healthy control subjects and that it will be possible to use MIF as a biomarker to improve disease monitoring and management." (PMID 35237527, 2021). "Receiver operating characteristic (ROC) analysis revealed that the serum MIF levels between leptospirosis cases and control subjects had an area under the curve (AUC) value of >0.9 (p < 0.0001)." (PMID 35237527, 2021). "In this study, we propose the consideration of serum macrophage migration inhibitory factor (MIF) for the diagnosis of leptospirosis because the expression of MIF is significantly elevated at the early stage of disease induction." (PMID 35237527, 2021). "Our data provided the first evidence of differential MIF levels in sera of leptospirosis patients, other febrile cases, and healthy control subjects." (PMID 35237527, 2021). "Taken together, the mRNA and protein expressions of MIF were significantly increased as the duration of infection increased, with MIF possibly driving the pathogenesis of leptospirosis." (PMID 35237527, 2021). "The present study determined the LD50 (20 mg/kg) of L. interrogans serovar Autumnalis strain N2 for the development of the experimental animal model of leptospirosis to analyze the expression profile of MIF during the disease." (PMID 35237527, 2021).